MIX23 (mitochondrial matrix import factor 23)
Synonyms: CCDC58; FLJ33273
Tractability: PROTAC: ubiquitination databases record sites on it.
Gene: Protein-coding gene on chromosome 3 (122,359,587 to 122,383,239, reverse strand). Ensembl gene ENSG00000160124.
Subcellular location (Human Protein Atlas): Mitochondria; Nucleoli
Gene Ontology:
Cellular component: mitochondrion; mitochondrial intermembrane space
Genetic constraint (gnomAD): Loss-of-function variants: 11 observed, 17.91 expected, observed/expected ratio (o/e) 0.61, 90% interval 0.39 to 1.02. The upper end of that interval is the gene's LOEUF score, 1.02, which puts it in group 4 of 6, group 1 being the genes least tolerant of losing a copy. Missense variants: 120 observed, 138.9 expected, observed/expected ratio (o/e) 0.86, 90% interval 0.74 to 1. Synonymous variants: 48 observed, 48.34 expected, observed/expected ratio (o/e) 0.99, 90% interval 0.79 to 1.26.
Homologues: Orthologues: macaque MIX23 (100% identical), rat Mix23 (99% identical), guinea pig MIX23 (98% identical), pig MIX23 (98% identical), dog MIX23 (97% identical), mouse Mix23 (97% identical), zebrafish mix23 (76% identical), tropical clawed frog mix23 (64% identical), Drosophila melanogaster Ccdc58 (42% identical).
Diseases named in the same sentence as MIX23 in open-access papers:
MIX23 is named in the same sentence as 18 diseases in open-access papers, as found by Europe PMC text mining. Sharing a sentence is not in itself a finding about the gene and the disease.
MIX23 shares sentences with these, for which no sentence is quoted: tumor (4 papers); breast carcinoma (3); cancer (3); endometrial cancer (2); acute myeloid leukemia (1); COVID-19 (1); diabetes (1); head and neck cancer (1); hepatocellular carcinoma (1); infection (1); leiomyosarcoma (1); liver cancer (1); lung adenocarcinoma (1); ovarian carcinoma (1); renal carcinoma (1); retinoblastoma (1); triple-negative breast carcinoma (1); uveal melanoma (1).